OR52L2P (olfactory receptor family 52 subfamily L member 2 pseudogene)
Description:
Odorant receptor.
Synonyms: OR52L2
Gene: Unprocessed pseudogene on chromosome 11 (6,057,286 to 6,058,275, reverse strand). Ensembl gene ENSG00000262980.
Subcellular location: Cell membrane